ETNK1 (ethanolamine kinase 1)
Description:
Highly specific for ethanolamine phosphorylation. May be a rate-controlling step in phosphatidylethanolamine biosynthesis.
Synonyms: EKI 1; EKI1; EKI; Nbla10396
Tractability: Antibody: the Human Protein Atlas places it where antibodies can reach. PROTAC: ubiquitination databases record sites on it; its protein half-life has been measured.
Gene: Protein-coding gene on chromosome 12 (22,625,075 to 22,690,665, forward strand). Ensembl gene ENSG00000139163.
Subcellular location: Cytoplasm
Subcellular location (Human Protein Atlas): Cytosol; Nucleoplasm; Plasma membrane
Pathways (Reactome):
Metabolism: Synthesis of PE
Gene Ontology:
Molecular function: ethanolamine kinase activity; protein binding
Biological process: phosphatidylethanolamine biosynthetic process
Cellular component: cytoplasm; membrane; cytosol
Genetic constraint (gnomAD): Loss-of-function variants: 5 observed, 28.48 expected, observed/expected ratio (o/e) 0.18, 90% interval 0.091 to 0.37. The upper end of that interval is the gene's LOEUF score, 0.37, which puts it in group 1 of 6, group 1 being the genes least tolerant of losing a copy. Missense variants: 261 observed, 342.29 expected, observed/expected ratio (o/e) 0.76, 90% interval 0.69 to 0.85. Synonymous variants: 120 observed, 124.23 expected, observed/expected ratio (o/e) 0.97, 90% interval 0.83 to 1.12.
Cancer hallmarks: escaping programmed cell death (suppresses)
Homologues: Orthologues: chimpanzee ETNK1 (100% identical), macaque ETNK1 (99% identical), rabbit ETNK1 (98% identical), dog ETNK1 (98% identical), pig ETNK1 (97% identical), guinea pig ETNK1 (96% identical), rat Etnk1 (95% identical), mouse Etnk1 (94% identical), tropical clawed frog etnk1 (80% identical), zebrafish etnk1 (71% identical), Drosophila melanogaster eas (45% identical), Caenorhabditis elegans ckc-1 (32% identical). Paralogues in human: ETNK2 (58% identical), CHKA (32% identical), CHKB (30% identical).
Diseases named in the same sentence as ETNK1 in open-access papers:
ETNK1 is named in the same sentence as 28 diseases in open-access papers, as found by Europe PMC text mining. Sharing a sentence is not in itself a finding about the gene and the disease. The quoted sentences say what the papers report.
chronic myelomonocytic leukemia (3 papers, 2016 to 2021). A myelodysplastic/myeloproliferative neoplasm which is characterized by persistent monocytosis, absence of a Philadelphia chromosome and BCR/ABL fusion gene, fewer than 20 percent blasts in the bone marrow and blood, myelodysplasia, and absence of PDGFRA or PDGFRB rearrangement. "Metabolite measurements revealed an averaged 5.2-fold decrease in the PtdEtn/PtdCho ratio of ETNK1-mutated atypical chronic myelomonocytic leukemia samples as compared to ETNK1 wild-type samples." (PMID 28083512, 2016). "Interestingly, an ETNK1 recurrent missense mutation was frequently found in systemic mastocytosis with eosinophilia and chronic myelomonocytic leukemia." (PMID 28083512, 2016).
gastric cancer (3 papers, 2021 to 2023). A primary or metastatic malignant neoplasm involving the stomach. "The underlying mechanism was the regulation of ethanolamine kinase 1 (ETNK1) expression by miR-708–3p, which bound to the 3′UTR of the ETNK1 gene in gastric cancer cells." (PMID 37809692, 2023). "Altogether, these results show that miR-708–3p negatively modulates ETNK1 expression in gastric cancer cells by directly targeting its 3′-UTR sequence." (PMID 37809692, 2023). "Using miRNA target forecast methods (targetscan.org and mirdb.org) to find miR‐708–3p target genes in gastric cancer progression, we identified ETNK1." (PMID 37809692, 2023). "In conclusion, we found a new miR-708–3p/ETNK1 pathway, which is crucial for gastric cancer progression and may be a new marker or target for gastric cancer therapy." (PMID 37809692, 2023). "Finally, a recovery assay confirmed that miR‐708–3p promoted gastric cancer cell progression by regulating ETNK1." (PMID 37809692, 2023). "ETNK1 is a chemosensitivity-related gene in gastric cancer cell lines." (PMID 37809692, 2023). "In conclusion, we identified a new miR-708–3p/ETNK1 pathway involved in gastric cancer progression." (PMID 37809692, 2023). "In gastric cancer, miR-199a-3p targeting ETNK1 may contribute to the malignancy of gastric cancer cells." (PMID 34606420, 2021). "Therefore, miR-708–3p promotes gastric cancer cell proliferation and migration by inhibiting ETNK1." (PMID 37809692, 2023). "Finally, the recovery assay results showed that ETNK1 overexpression could slow miR-708-3p-induced gastric cancer progression." (PMID 37809692, 2023).
myeloid neoplasm (3 papers, 2020 to 2025). Proliferation of myeloid cells originating from a primitive stem cell. "ETNK1 mutation is an early event in myeloid neoplasms, often co-occurring with ASXL1, TET2, EZH2, RUNX1, and SRSF2 mutations." (PMID 40074445, 2025). "Recurrent somatic mutations in ETNK1 (Ethanolamine-Kinase-1) were identified in several myeloid malignancies and are responsible for a reduced enzymatic activity." (PMID 33230096, 2020).
glaucoma (2 papers, 2025). Increased pressure in the eyeball due to obstruction of the outflow of aqueous humor. "ETNK1, VMAC, NEXN, and SUN1 were identified as glaucoma-associated autoantibodies based on their plasma levels and positive rates." (PMID 41463042, 2025). "As a result, ethanolamine kinase 1 (ETNK1), vimentin-type intermediate filament-associated coiled-coil protein (VMAC), nexilin (NEXN), and Sad1 and UNC84 Domain Containing 1 (SUN1) were identified as glaucoma-associated autoantibodies." (PMID 40149693, 2025). "In this study, a cohort of cataract, NTG, and POAG patients was examined by CWPA for plasma autoantibodies, and four new autoantibodies, ETNK1, VMAC, NEXN, and SUN1, were detected as glaucoma-related." (PMID 40149693, 2025).
glioma (2 papers, 2018 to 2022). A benign or malignant brain and spinal cord tumor that arises from glial cells (astrocytes, oligodendrocytes, ependymal cells).
leukemia (2 papers, 2020 to 2024). A malignant (clonal) hematologic disorder, involving hematopoietic stem cells and characterized by the presence of primitive or atypical myeloid or lymphoid cells in the bone marrow and the blood. "We found that 8 genes overlapped, and O-GlcNAc transferase (OGT) and ETNK1 were associated with mitochondrial function and leukemia cell survival." (PMID 38609495, 2024). "Further studies will be required to assess if the treatment with tigecycline or P-Et is able to reduce the risk of progression of ETNK1+ leukemias." (PMID 33230096, 2020). "ETNK1 mutations are recurrent in leukemia but how they contribute to oncogenesis is still unclear." (PMID 33230096, 2020).
lung adenocarcinoma (2 papers, 2019 to 2022). A carcinoma that arises from the lung and is characterized by the presence of malignant glandular epithelial cells. "Elevated ETNK1 (ethanolamine kinase 1), is correlated with worse prognosis and survival among lung adenocarcinoma patients." (PMID 35563655, 2022). "The CDP-ethanolamine Kennedy pathway genes ETNK1, PCYT2, and SELENO1 are upregulated in both lung adenocarcinoma and squamous cell carcinoma tissues." (PMID 35563655, 2022).
breast carcinoma (1 paper, 2024). "The inhibition of ETNK1 by miR-103a-3p may facilitate the progression of breast cancer." (PMID 38807590, 2024).
breast tumors (1 paper, 2023). "The accumulation of phosphoethanolamine in breast tumors is related to the increased activity of ethanolamine kinase 1 enzyme." (PMID 36831625, 2023).
cataract (1 paper, 2025). Partial or complete opacity of the crystalline lens of one or both eyes that decreases visual acuity and eventually results in blindness. "In discrimination between the POAG and cataract groups, the AUCs of ETNK1 and VMAC were calculated to be 0.820 (95%CI: 0.733–0.907) and 0.889 (95%CI: 0.818–0.959), respectively." (PMID 40149693, 2025).
chronic myeloid leukemia (1 paper, 2021). "Atypical chronic myeloid leukemia (aCML) is most known for granulocytosis with marked dysplasia and often harbors ASXL1 mutations, but SETBP1 and ETNK1 are more specific to this disease." (PMID 35844680, 2021).
epilepsy (1 paper, 2020). A brain disorder characterized by episodes of abnormally increased neuronal discharge resulting in transient episodes of sensory or motor neurological dysfunction, or psychic dysfunction. "The eas encodes an ethanolamine kinase involved in mechanosensory behavior, nervous system development and the phosphatidylethanolamine metabolic process, although its human orthologue ethanolamine kinase 1 (ETNK1) is not related to epilepsy." (PMID 32899411, 2020).
head and neck cancer (1 paper, 2023). A primary or metastatic malignant neoplasm affecting the head and neck. "However, we saw cases such as ETNK1 in head and neck cancer, where meQTLs implicated a gene that has not been considered a factor promoting progression." (PMID 41584369, 2023).
malignant glioma (1 paper, 2022). A grade III or grade IV glioma arising from the central nervous system. "The eleven genes within the circadian rhythm pathway (AC020907.1, Y_RNA, TMEM72‐AS1, KRT16P2, DLX6‐AS1, AP002414.1, hsa‐miR‐424, TBPL1, NPAS2, CRY2, and ETNK1) were used to construct a model to evaluate the importance of these genes in malignant glioma." (PMID 35194922, 2022). "During the process of illustrating the circadian rhythm pathway, among the 6 coding genes, we exhibited the biological functions of TBPL1, NPAS2, CRY2, and ETNK1; therefore, what are the roles of VPS33B and C9ORF40 in malignant glioma?" (PMID 35194922, 2022).
pancreatic cancers (1 paper, 2023). "In studies investigating the roles of ethanolamine kinases (Etnk-1 and −2), we found that breast and pancreatic cancer cells showed higher PE compared with their nonmalignant counterparts, with Etnk-1 a major cause of the elevated PE levels in these cancer cells." (PMID 35262263, 2023).
tumor (7 papers, 2016 to 2025). "ASXL1 mutations are frequent, with the disease displaying a higher prevalence of ETNK1, SETBP1, and EZH2 mutations in comparison to other MDS/MPN overlap neoplasms." (PMID 37370785, 2023). "miRNAs modulate the expression of numerous metabolic factors and enzymes, such as SREBF2, AKT2, G6PD, CPS1, FADS1, and ETNK1, which alter tumor cell responses to chemotherapeutic treatments." (PMID 27861141, 2016). "Leveraging advanced bioinformatics techniques, the identification of 12 crucial genes (ETNK1, BICRA, IL-1R1, KDM3A, ARID2, GSK3β, EZH2, NOTCH1, SMARCA4, FOS, CREB1, CASP3) associated with the tumor-suppressing miR-101-3p network stands out as a notable achievement." (PMID 40074445, 2025). "The gene expression analysis revealed that several hub genes, such as ETNK1, KDM3A, EZH2, SMARCA4, and CASP3, were significantly overexpressed in HCC tissues, suggesting their potential roles in tumor progression and as biomarkers for HCC." (PMID 40074445, 2025). "Recent research has identified key enzymes involved in CD4+ T cell differentiation and the Kennedy pathway—ETNK1, PCYT2, and SELENOI—suggesting a potential correlation between SELENOI and tumor immunity." (PMID 39669976, 2024). "Both ETNK1 and CHKA genes were found to be up-regulated in tumor tissue, but ETNK1 genes also showed elevated expression in lymphoid tissue (Fig. 4f5, f6, g5, g6)." (PMID 37164975, 2023). "We identified 42 and 16 TSGs monoallelically deleted in P2 and P5, respectively, including several TSGs deleted in both tumor samples (ARHGEF10, CDKN1B, ETNK1, ETV6, LEPROTL1, NRG1, PTPN6, and WRN) and many TSGs co-deleted in the same subclone as well as across multiple subclones." (PMID 38658552, 2024).
hematological neoplasms (1 paper, 2020). "As the 293 is not a hematological line and ETNK1 was found mutated in hematological neoplasms, we sought to replicate our data in the myeloid TF-1 model." (PMID 33230096, 2020).
ETNK1 also shares sentences with these, for which no sentence is quoted: cancer (4 papers); systemic mastocytosis (2); diffuse large B-cell lymphoma (1); eosinophilia (1); granulocytosis (1); Macrocephaly (1); open-angle glaucoma (1); renal cell carcinoma (1); seminoma (1); squamous cell carcinoma (1); Thrombocytopenia (1).